AR (androgen receptor)
Diseases named in the same sentence as AR in open-access papers (continued):
Sharing a sentence is not in itself a finding about the gene and the disease.
melanoma (continued). "WB analysis in a panel of melanoma-derived cells confirms that AR is prevalently expressed in cells derived from lymph node or subcutaneous metastasis (MEL-CAL, AMM16, WM266-4 and LCM-mel cells)." (PMID 39837817, 2025). "Future studies are expected to elucidate the relative functional contribution of these signaling mechanisms to AR+ vs. AR- melanomas under different stage- and therapy-specific contexts." (PMID 38326303, 2024). "Our findings suggest that in melanoma cells, stimulation of AR activity at least partially bypasses androgen." (PMID 38326303, 2024). "In melanoma, lncRNAs that bind to the androgen receptor and regulate the transcription of growth-regulatory genes, such as SRA-like Non-coding RNA (SLNCR), contribute to poorer prognosis for men compared to women." (PMID 38095719, 2024). "Taken together, these data demonstrate that consistent with classical AR activation and function, in melanoma cells, androgen-activated AR accumulates in the nucleus where it exhibits transcriptional activity." (PMID 38326303, 2024). "Supplemental testosterone mitigates the effects of BRAF + MEK inhibition, and blockade of the androgen receptor (AR) promotes the anti-tumor activity of BRAF + MEK inhibitors in BRAF Class 1 mutant melanoma mouse models." (PMID 38275886, 2024). "We sought to delineate if and how androgen-induced and transcriptionally active AR impacts melanoma biology, and thus, tumorigenic capacity." (PMID 38326303, 2024). "Our work, together with these previous studies highlight how AR signaling can potently stimulate melanoma tumorigenesis, growth, distal metastasis, and therapeutic resistance." (PMID 38326303, 2024). "The mechanism that we delineate appears to help explain how androgen/AR signaling shapes melanoma malignancy, enhancing invasive and metastatic capacity by inducing tumorigenic fucosylation." (PMID 38326303, 2024). "Consistent with the effects of ARi, genetically knockdown of endogenous AR also blunted migration capacity in melanoma cells." (PMID 38326303, 2024). "Here, we report an intersection between AR-regulated transcription and protein fucosylation that plays a crucial mechanistic role in driving the androgen-stimulated metastatic capacity of melanoma." (PMID 38326303, 2024). "Regarding melanoma motility, AR was previously reported to promote melanoma metastasis via transcriptional upregulation of miRNA-539-3p, which impacts MITF and AXL signaling." (PMID 38326303, 2024). "Culture of AR+ WM793 melanoma cells in steroid hormone-depleted medium (10% charcoal-stripped serum (CSS)) inhibited cell viability—an effect that was entirely reverted by DHT supplementation (left)." (PMID 38326303, 2024). "We identified fucosyltransferase 4 (FUT4) as a key transcriptional target of AR that plays a crucial role in mediating androgen-stimulated invasiveness by disrupting cell-cell adhesion complexes in melanoma." (PMID 38326303, 2024). "We assessed AR expression and its correlations with downstream effectors in human melanoma specimens by immunofluorescence staining analysis of a 100-case melanoma tissue microarray (TMA)." (PMID 38326303, 2024). "Together, these findings support the role of AR in driving aggressive melanoma pathogenesis via fucosylation of L1CAM and abrogation of AJ complexes in male patients." (PMID 38326303, 2024). "For example, SLNCR1 has been shown to promote melanoma invasion and growth through its interaction with androgen receptor and EGR1." (PMID 38561355, 2024). "The findings are of functional significance, as live-cell imaging assays showed that treatment with either AR inhibitors blunted the proliferation of BRAFi-resistant melanoma cells and, at the same time, induced cell death." (PMID 37838724, 2023).
melanoma (continued). "Consistent with previous studies, a large number of BRAFi-resistant colonies emerged in cultures of parental melanoma cells treated with the BRAFi alone, which was significantly reduced in cultures concomitantly treated with AR inhibitors." (PMID 37838724, 2023). "Androgen receptor (AR), for example, was recently reported to exhibit effects of promoting cell proliferation, melanoma metastasis, and drug resistance in melanoma cells and mouse models." (PMID 36833272, 2023). "In melanoma patients, AR signaling induction highly impairs efficacy of BRAF/MEK targeted therapy, which provides the explanation of why female patients display significantly higher response rates." (PMID 37434223, 2023). "Altogether, the findings indicate that AR overexpression in melanoma cells effectively counteracts growth suppression by BRAF inhibition." (PMID 37838724, 2023). "Immunoblot analysis showed that AR expression was increased in various melanoma cell lines upon 48-h, 72-h, and one-week-long DAB treatment." (PMID 37838724, 2023). "Regarding the mechanisms involved in the induction of AR expression, immunofluorescence analysis demonstrated that this occurs in the vast majority of melanoma cells at early times to DAB treatment." (PMID 37838724, 2023). "In contrast to the inhibitory effects of AR inhibitors on the growth of BRAFi-resistant melanoma cells, the treatment with the AR agonist dihydrotestosterone (DHT) significantly increased their proliferation." (PMID 37838724, 2023). "Most of previous studies of AR in melanoma suggested that AR promoted tumor proliferation, metastasis, and drug resistance." (PMID 36833272, 2023). "Similar results were observed when silencing AR in three BRAFi-resistant melanoma lines by two different shRNA vectors." (PMID 37838724, 2023). "Conversely, treatment with AR inhibitors suppresses the proliferation and tumorigenicity of BRAFi-resistant melanoma cells, enhancing CD8+ T cell infiltration." (PMID 37838724, 2023). "Melanoma cells pretreated with the AR inhibitors produced tumors of significantly smaller size than controls as observed with the human cells." (PMID 37838724, 2023). "Irrespective of expression levels, silencing of the AR gene and pharmacological inhibition of AR activity suppresses proliferation and induces cellular senescence of a relatively large panel of melanoma cells from both male and female patients." (PMID 37838724, 2023). "The data suggested that ADRB2 and Adrb2 genes which encode the β2AR in human and mouse, respectively, was the predominant β androgen receptor in the melanoma cells." (PMID 38036925, 2023). "One noteworthy lncRNA, SLNCR, has been observed to bind to the androgen receptor (AR), resulting in increased melanoma proliferation by modulating several growth regulatory genes." (PMID 37629553, 2023). "A previous study has demonstrated that AR is important in promoting the proliferation of melanoma by down‐regulating MITF." (PMID 37070131, 2023). "We reported that androgen receptor (AR) activity is required for melanoma cell proliferation and tumorigenesis." (PMID 37838724, 2023). "Increased AR expression is sufficient to render melanoma cells BRAFi-resistant, eliciting transcriptional changes of BRAFi-resistant subpopulations, including elevated EGFR and SERPINE1 expression, of likely clinical significance." (PMID 37838724, 2023). "We show here that AR expression is markedly increased in BRAFi-resistant melanoma cells, and in sensitive cells soon after BRAFi exposure." (PMID 37838724, 2023). "In the present study, we assessed the translational significance of suppressing AR signaling in the context of melanoma response to targeted drug treatments, specifically BRAF inhibitors." (PMID 37838724, 2023). "Next to the AR gene itself, SERPINE1, an established TGF-ß target with pro-tumorigenic functions, was the single most upregulated gene in all three AR overexpressing melanoma cells." (PMID 37838724, 2023).
melanoma (continued). "To assess the clinical significance of the results, we analyzed the transcriptomic profiles of melanoma cohorts, finding a strong positive correlation between expression levels of the AR and EGFR genes in multiple data sets." (PMID 37838724, 2023). "The AR expression is related to a poor prognosis in patients affected by melanoma with the acquisition of a metastatic phenotype." (PMID 36941697, 2023). "Our rationale was that short-term exposure of melanoma cells to BRAF inhibitors leads to the significant induction of AR expression, accompanied by gene expression changes that, however, are insufficient to cause BRAFi resistance." (PMID 37838724, 2023). "AR was recently studied in melanoma cells, with a function of promoting proliferation, tumorigenesis, metastasis, and drug resistance, which is opposite to our findings." (PMID 36833272, 2023). "Inhibition of AR expression or activity blunts changes in gene expression and suppresses proliferation and tumorigenesis of BRAFi-resistant melanoma cells, promoting clusters of CD8+ T cells infiltration and cancer cells killing." (PMID 37838724, 2023). "In our recent work, we have found that the androgen receptor (AR) gene is heterogeneously expressed in melanoma cells, both at the single-cell intralesional level and among lesions at various stages of the disease." (PMID 37838724, 2023). "Further investigation on these shared and distinct functions of AR in melanoma patients will help us to develop precise treatment strategies." (PMID 36833272, 2023). "Consistent with the transcriptomic results, RT-qPCR and immunoblot analysis showed a marked increase in SERPINE1 (PAI-1) levels in all tested melanoma cell lines upon AR overexpression." (PMID 37838724, 2023). "AR down-modulation or pharmacological inhibition suppress melanoma genesis, through an increase in intratumoral infiltration of macrophages and, in an immune-competent mouse model, cytotoxic T cells." (PMID 36614041, 2022). "Several studies showed that T, the most abundant androgen in males, promotes different cell types proliferation, including fibroblasts, visceral preadipocytes, glioblastoma-derived cells and melanoma through the AR." (PMID 36614041, 2022). "Although AR signaling has been largely studied in tumorigenesis in prostate, breast, bladder, kidney, lung, and liver, little is known about its role in melanoma." (PMID 36614041, 2022). "AR, indeed, plays a key role in increasing melanoma cell invasion in multiple cell lines in vitro and in a mouse model in vivo." (PMID 36286041, 2022). "The same authors investigated the presence of AR in two other human melanoma cell lines, IIB-MEL-LES and IIB-MEL-IAN, as well as in biopsies from human metastatic melanoma." (PMID 36614041, 2022). "Subsequently, in 1995, the implication of functional AR in human melanoma cell line IIBMEL-J was proved by growth inhibition in vitro and in vivo with antiandrogens." (PMID 36614041, 2022). "Genetic or pharmacological suppression of AR activity in melanoma cells hinders their proliferation." (PMID 36286041, 2022). "Studies have demonstrated that androgen receptor (AR) is important in promoting the metastasis of melanoma by targeting MITF." (PMID 35452181, 2022). "While the total number of CD4+ T cells (CD45+ CD3+ CD4+) was not significantly different, that of CD4+ regulatory T cells (CD45+ CD3+ CD4+ FoxP3+) was significantly decreased in in AR-silenced YUMM1.7 melanomas." (PMID 33112375, 2021). "The analysis was extended to a panel of other melanoma cell lines and primary melanoma cells with different levels of AR expression by RT-qPCR." (PMID 33112375, 2021). "The shRNA gene silencing effects were suppressed in melanoma cells concomitantly infected with an AR-overexpressing lentivirus, which was by itself sufficient to enhance proliferation of primary melanocytes as well as melanoma cells with low AR expression." (PMID 33112375, 2021).
melanoma (continued). "In vivo, upon intradermal injection into immune-competent mice, melanoma cells with silenced AR formed much smaller tumors than controls, with substantially reduced melanoma cell density and proliferative index." (PMID 33112375, 2021). "We have shown here that sustained AR signaling is key for melanoma cell proliferation potential and tumorigenesis in cells from both male and female individuals." (PMID 33112375, 2021). "Next, we established an AR gene-silencing signature of 155 genes, which were significantly and concordantly modulated by AR silencing in all three melanoma cell lines." (PMID 33112375, 2021). "Dissociation of tumor cells followed by FACS analysis showed a significant increase of macrophages (CD45+ Gr-1− F4/80+ CD11b+) in AR-silenced YUMM1.7 melanomas, consistent with what we observed with human cells in immune-compromised mice." (PMID 33112375, 2021). "The AZD3514 inhibitory effects were confirmed by treatment of a larger panel of melanoma cell lines and primary melanoma cells with different levels of AR expression, consistent with the basal protective function investigated below." (PMID 33112375, 2021). "To assess the net effects of AR inhibitors on melanoma cells in the presence of surrounding HDFs, we used an in vitro cancer/stromal cell expansion assay based on the coculture in Matrigel of fluorescently labeled cells." (PMID 33112375, 2021). "Immunostaining of cultured cells also showed a variation in AR protein expression among various melanoma cell lines and primary melanoma cells derived from male or female patients, with AR levels being uniformly low in primary melanocytes." (PMID 33112375, 2021). "Irrespective of expression levels, genetic and pharmacological suppression of AR activity in melanoma cells blunts proliferation and induces senescence, while increased AR expression or activation exert opposite effects." (PMID 33112375, 2021). "Mass infection of dCas9-KRAB–expressing melanoma cells with two lentiviruses with AR-targeting sgRNAs significantly reduced AR protein levels, decreased clonogenicity, and induced cellular senescence, reproducing the effects of AR gene silencing." (PMID 33112375, 2021). "To discover the function of the lncRNAs in the AR-induced melanoma development, we studied the expression of lncRNAs in AR-overexpressed melanoma cells using lncRNA sequencing analysis." (PMID 33875645, 2021). "In support of this possibility are our further findings that, in the iLINCS database, similar gene expression profiles are triggered by treatment of melanoma cells with AR inhibitors and conventional DNA-damaging agents, specifically TOPO inhibitors." (PMID 33112375, 2021). "Expansion of melanoma cells admixed with HDFs was significantly reduced by treatment with the AR inhibitor AZD3514, consistent with the efficacy of this compound in the in vivo assays shown further below." (PMID 33112375, 2021). "Another study described a decreased AR level in several tumors, including melanoma, when compared to the normal tissue counterparts, and with intratumoral receptor levels higher in males than in females." (PMID 32645881, 2020). "Many reports demonstrated AR involvement in melanoma growth and invasion in vitro and in vivo (right), eventually involving immune response blockage." (PMID 32645881, 2020). "A large body of evidence supported AR involvement in melanoma incidence and progression, although a clear correlation between AR expression in melanoma and bad prognosis is lacking." (PMID 32645881, 2020). "Although less studied than ERs, the expression of AR was assessed in several melanoma cell lines and in human metastatic specimens, where high receptor levels were detected." (PMID 32645881, 2020). "Despite the long-held belief that AR contributes to melanomagenesis, there has been little progress in determining the role of AR in melanoma etiology." (PMID 31116991, 2019).
melanoma (continued). "In direct support of an oncogenic function for AR, we recently showed that AR increases melanoma invasion through transcriptional upregulation of the matrix metalloproteinase MMP9." (PMID 31116991, 2019). "Performing AR ChIP-seq from MSTCs is technically challenging because of low AR expression; thus, we performed AR ChIP-seq from higher AR-expressing A375 melanoma cells." (PMID 31116991, 2019). "Because SLNCR imparts oncogenic function to AR in the absence of canonical androgen-induced signaling, we sought a more complete mechanistic understanding of AR function as a possible explanation for the observed melanoma sex bias." (PMID 31116991, 2019). "The observations described here provide the first global characterization of a role of AR in melanoma biology and confirm that AR binds to many melanoma-relevant genes." (PMID 31116991, 2019). "ChIP-seq reveals that ligand-free AR is enriched on SLNCR-regulated melanoma genes and that AR genomic occupancy significantly overlaps with EGR1 at consensus EGR1 binding sites." (PMID 31116991, 2019). "Here we examine ligand-independent, SLNCR-regulated AR function in melanoma and find that AR directly binds many SLNCR-regulated genes." (PMID 31116991, 2019). "Incubation of biotinylated, full-length SLNCR1 with A375 melanoma cell lysate followed by streptavidin pulldown enriched AR and EGR1." (PMID 31116991, 2019). "Combined with the fact that primary male melanomas express higher AR protein than female melanomas (p= 0.046), it is likely that oncogenic AR activity contributes to the observed gender differences." (PMID 31116991, 2019). "Our work highlights the importance of SLNCR in mediating AR’s oncogenic effects in melanoma, particularly in the context of the melanoma gender bias." (PMID 31116991, 2019). "Consistent with previous studies implicating AR in melanoma cell proliferation, the anti-androgen flutamide, which competes with androgen for binding to AR, significantly decreased melanoma cell proliferation (p < 0.0001)." (PMID 31116991, 2019). "Here we comprehensively interrogated the role of AR in melanoma gene regulation, identifying many AR-regulated tumor suppressors and oncogenes." (PMID 31116991, 2019). "Immunohistochemical staining with androgen receptor and adipophilin were used to separate squamous cell carcinomas, melanomas, sebaceous tumors, and basal cell carcinomas." (PMID 28187442, 2017). "AR reactivity was present in 40% of melanomas; however, it was also observed in 41% of normal skin [S29]." (PMID 25595907, 2015). "In contrast, a different report (N=142 patients with malignant melanoma) discerned AR positivity in only 4% of cases [S30]." (PMID 25595907, 2015). "Furthermore, we and others have demonstrated that BRAF-/MEK-targeted therapies for the treatment of advanced melanoma induce AR expression in males and females; however, treatment outcomes are worse in male patients." (PMID 41486951, 2026). "In regard to SKCM, others have reported that melanoma cells rely on sustained AR signaling for proliferation and tumorigenesis, and downregulation correlated with enhanced immune cell infiltration intratumorally in both sexes, which is consistent with the findings in the current study." (PMID 41486951, 2026). "AR promotes melanoma invasiveness through multiple integrated pathways." (PMID 40940929, 2025). "AR upregulation is a key adaptive mechanism in BRAF-mutant melanoma." (PMID 40940929, 2025). "In this study, AR+ melanoma patients were shown to have worse overall survival." (PMID 41228208, 2025). "Overall, AR represents a compelling and underexplored axis in melanoma pathogenesis and therapy." (PMID 40940929, 2025).